RNF43 (ring finger protein 43)
Diseases named in the same sentence as RNF43 in open-access papers (continued):
Sharing a sentence is not in itself a finding about the gene and the disease.
cancer (continued). "Altogether, this data indicated that RNF43/ZNRF3 loss predisposes to cancer due to altered lipid metabolism and defective tissue regeneration (hepatocyte maturation) upon cumulative rounds of tissue damage." (PMID 35039505, 2022). "Comprehensive screening of 135 RNF43 missense and frameshift mutations in multiple human cancers revealed that all of the frameshift mutations and almost all missense mutations are located in the RING domain." (PMID 36866106, 2022). "This evidence proves that RNF43/ZNRF3 loss of function in cancer cells is still dependent on Wnt ligand stimulation." (PMID 34000297, 2021). "We capitalized on the RNA-seq data and used eVIP Pathway analysis to find which pathways are impacted in each RNF43 variant to gain further insight into the functional changes of each cancer-associated variant." (PMID 34214079, 2021). "Here, we found two recurrent frameshift mutations in RNF43 that have different effects on gene function where one mutation causes multiple cancer pathways to be activated." (PMID 34214079, 2021). "We conclude that onco‐RNF43 mutations confer decreased dependence on Wnt and Rspo niche factors, a hallmark of cancer cell growth." (PMID 32965059, 2020). "In accordance, an RNF43 cancer variant carrying a CK1‐binding site deletion (ΔS486‐G489>R; cBioportal) displayed LOF effects (Fig EV4G)." (PMID 32965059, 2020). "Insight in the mechanisms by which individual RNF43 mutations contribute to cancer development and progression therefore is vital for the understanding of patient‐specific disease mechanisms and the development of precision oncology strategies." (PMID 32965059, 2020). "In fact, RNF43(3SA) displayed similar oncogenic properties as an established cancer-associated R127P mutation in RNF43, which is within the extracellular protease-associated (PA) domain and abolishes inhibition of Wnt signalling." (PMID 32934222, 2020). "Truncating mutations of RNF43 were also observed in colorectal adenocarcinoma, predominantly in microsatellite unstable cancers, and showed a mutual exclusivity pattern with inactivating APC mutations." (PMID 32245111, 2020). "As this Wnt receptor suppressor activity of RNF43 locates to its membrane‐proximal regions, the functional relevance of truncating cancer mutations that remove more distal parts of the cytosolic tail thus far has remained unclear." (PMID 32965059, 2020). "This vulnerability has offered an opportunity to treat human cancers that are genetically defined by RNF43 mutations with PORCN inhibitors." (PMID 32965059, 2020). "To address this issue, we expressed RNF43 cancer variants carrying incremental C‐terminal truncations in HEK293T cells and monitored their impact on Wnt‐induced β‐catenin‐mediated transcription." (PMID 32965059, 2020). "Here, the authors report that RNF43 phosphorylation at a serine triplet is required for the negative regulation of Wnt signalling and that the phosphorylation of RNF43 suppresses cancer-associated oncogenic RNF43 mutants." (PMID 32934222, 2020). "Reassuringly, RNF43, which has two mutational hotspots, was successfully identified as a cancer driver." (PMID 32384699, 2020). "We conclude that truncated RNF43 cancer variants affect a molecular step positioned downstream of the Wnt receptors and upstream of β‐catenin‐mediated transcription." (PMID 32965059, 2020). "Contrary to this paradigm, we identify a class of RNF43 truncating cancer mutations that induce β‐catenin‐mediated transcription, despite exhibiting retained Wnt receptor downregulation." (PMID 32965059, 2020). "Accordingly, cancer cells with loss of RNF43 were more proliferative, leading to a higher Ki67 activity." (PMID 31248166, 2019).
cancer (continued). "Enhanced Wnt receptor expression due to mutational inactivation of the ubiquitin ligases RNF43/ZNRF3 recently emerged as a leading cause for cancer development." (PMID 30664649, 2019). "In the COSMIC cancer database, approximately half of the 1,036 mutations of RNF43 identified from all cancer types are either non-sense or frameshift mutations." (PMID 31811196, 2019). "Inactivating gene mutations in the pathway, such as Rnf43 in pancreatic cancer and Znrf3 in adrenocortical cancer or additional cancers, have implicated new links between Wnt signaling and cancer transformation." (PMID 31167446, 2019). "This study provides evidence that somatic mutation of RNF43 is the driver genetic alteration that links chronic inflammation and cancer development in about 10% of CACs." (PMID 29416670, 2018). "A previous study found that most RNF43 mutations in sporadic CRCs occur in cancers with high microsatellite instability (MSI)." (PMID 29416670, 2018). "The profile revealed that RNF43 was mutated and functioned as a cancer driver in about 10% of cases." (PMID 29416670, 2018). "Our study indicates that somatic mutation of RNF43 is the molecular link between chronic inflammation and cancer development in approximately 10% of CAC cases." (PMID 29416670, 2018). "Recent reports showed that RNF43 encoded an E3 ubiquitin ligase that negatively regulated Wnt signaling and played a crucial role in the development of various cancers." (PMID 29293510, 2018). "The findings that RNF43 functions as an inhibitor against the Wnt signaling pathway are consistent with its mutation in cancers." (PMID 28446252, 2017). "Eight BRAF mutant/MSS cancers (8/33, 24.2%) had RNF43 mutations including 2 point mutations and 6 frameshift mutations that were located throughout the gene." (PMID 27661107, 2016). "From those cancers that were assessed for presence of mutation, a subset of cancers were examined for RNF43 and ZNRF3 transcript expression levels." (PMID 27661107, 2016). "This likely reflects the higher RNF43 mutation rate in MSI cancers and therefore the inability to upregulate RNF43 in response to elevated Wnt signal, as is common in BRAF wild type cancers." (PMID 27661107, 2016). "In this review, we will discuss the biology of the R-spondin-ZNRF3/RNF43 signaling module, cancer-associated alterations of this signaling module, and their value as biomarkers to identify Wnt-addicted tumors." (PMID 27338477, 2016). "Cytoplasmic RNF43 staining was significantly less common in cancers harbouring the X659fs mutation compared to that in wild type cancers (RNF43 cytoplasmic positive cancers: 11/27, 41% vs 35/49, 71% respectively, p=0.01)." (PMID 27661107, 2016). "BRAF mutant/MSS cancers had a moderate proportion of RNF43 mutations (8/33; 24.2%), whilst BRAF wild type cancers had the least frequent mutations compared to the BRAF mutant subgroups (3/79, 3.8%) (p<0.0001)." (PMID 27661107, 2016). "The RNF43 wild type cancer cell lines all harbour either APC or β-catenin mutations which would be predicted to render them insensitive to upstream inhibition of the Wnt signal, as was observed." (PMID 27661107, 2016). "It is also noteworthy that three cancer-associated mutations reported for RNF43 map to the corresponding dimer interface observed in the ZNRF3ecto crystal structures, suggesting the characteristics of this surface have functional relevance in RNF43 as well." (PMID 24225776, 2013). "In addition, we have better defined the mode of action through which ZNRF3 and RNF43 mutations contribute to cancer formation, including at endogenous expression levels." (PMID 39674817, 2025). "In addition, cancers with alterations in RNF43, CTNNB1, and TCF7L2 displayed high rates of mutations in receptor tyrosine kinases, MMR-associated genes and DDR-associated genes, independently of the presence or absence of concomitant APC alterations." (PMID 40061138, 2025).
cancer (continued). "Downregulation or mutation of the ring finger protein (RNF)-43, a negative regulator of the Wnt pathway, serves as a poor prognostic factor for various cancers; however, its specific mechanisms in GC remain unclear." (PMID 41487817, 2025). "Currently, it remains unclear to what extent truncating mutations in the RNF43 gene contribute to activation of WNT signaling in cancer." (PMID 40687798, 2025). "Literature evidence reports that RNF43 (ring finger protein 43) gene mutations could serve as predictive biomarkers of response to certain anti-cancer therapies." (PMID 40735046, 2025). "The type of BRAF mutation, and the presence of concomitant RNF43 mutation, may explain some of the differences in cancer behaviour." (PMID 41002577, 2025). "Literature evidence reports that RNF43 mutations could serve as predictive biomarkers of response to certain anti-cancer therapies." (PMID 40735046, 2025). "A second group of cancers acquires mutations in the homologous RNF43 and ZNRF3 genes." (PMID 39674817, 2025). "RNF43 (Ring finger protein 43) is an E3 ubiquitin-protein ligase that inhibits overactivation of the Wnt pathway, and RNF43 mutations lead to permanent activation of the Wnt pathway in cancer cells." (PMID 40860811, 2025). "Indeed, truncation or missense mutations in rnf43 that harm the negative regulation of Wnt signaling have been found in cancer." (PMID 39125653, 2024). "WNT hypersensitivity has emerged as a major driver of cancer growth, which may be caused either by mutational inactivation of RNF43/ZNRF3 or overexpression of RSPO-fusion proteins." (PMID 38969364, 2024). "Mutations in RNF43 gene activate the WNT pathway in cancer cells." (PMID 38225722, 2024). "Here, we found that RNF43‐mutated cancer cells exhibited increased MEK activity." (PMID 38225722, 2024). "In fact, the detection of RNF43 mutations in the blood of cancer patients provides a wealth of information that can be used for the selection of patients that might benefit the most from anti-Wnt therapy." (PMID 39125653, 2024). "Besides, the results also demonstrated that the expression of RNF43 was distinctly correlated with the immune-associated cell infiltration levels of macrophages in 4 types of cancer." (PMID 37848933, 2023). "Mutation of RNF43 has been observed frequently in various types of human cancers." (PMID 37409251, 2023). "Loss-of-function mutations in Rnf43 and Znrf3 are frequently found in cancer cells." (PMID 37682999, 2023). "In addition, the mutation count and TMB levels in the RNF43-altered group were significantly higher than those in the unaltered group in TCGA pan-cancer and TMB and Immunotherapy cohorts respectively." (PMID 37848933, 2023). "RNF43 mutations were also identified in cancers in the ovary, stomach, and pancreas." (PMID 35040131, 2022). "In addition, RNF43 mutations were detected in MSI cancers in the stomach, esophagus, and uterine endometrium, suggesting that RNF43 mutations are major drivers of MSI‐type cancer." (PMID 35040131, 2022). "The E3 ubiquitin ligases RNF43/ZNRF3 are often mutated in cancer but their precise contribution to liver disease is unknown." (PMID 35039505, 2022). "Inconsistencies in how CRCs with PTPRK-RSPO3 fusions and CRCs with RNF43 mutations enhance their sensitivity to extracellular WNT signaling may be due to different selective pressures during cancer evolution." (PMID 34873211, 2021). "Another study showed that cancer cell lines with inactivating RNF43 mutations could be growth-inhibited with PORCN inhibitors in vitro and in vivo." (PMID 34000297, 2021). "Additionally, preclinical cancer models have shown the responsiveness of RNF43 mutations to Wnt inhibitors, several of which are in clinical trials." (PMID 34594355, 2021). "Taken together, these data suggest that the combination of olaparib and ETC‐159 may be an effective treatment for some Wnt high cancers with inactivating RNF43 mutations that are resistant to monotherapy with Wnt pathway inhibitors." (PMID 33660437, 2021).
cancer (continued). "This brings up the question of whether these RNF43 mutations confer WNT dependence onto these cancers." (PMID 34000297, 2021). "Truncating RNF43 mutations may alter WNT signaling, but these are predominantly present in mismatch repair deficient BRAF mutant cancer, and there is controversy as to whether RNF43 mutation affects canonical WNT signaling." (PMID 32384699, 2020). "Importantly, our findings unveil a class of RNF43 truncating cancer mutations that interfere with this second suppressor role to drive inappropriate Wnt pathway activation, by employing a mechanism distinct from that of RNF43 LOF or APC mutations." (PMID 32965059, 2020). "RNF43 is frequently mutated in cancers and negatively regulates Wnt signalling." (PMID 32934222, 2020). "In contrast, we found that four naturally occurring cancer-associated mutations within the SSSDS sequence inhibit or are predicted to inhibit RNF43-mediated repression of Wnt/β-catenin signalling, suggesting that loss of RNF43 phospho-regulation contributes to tumorigenesis." (PMID 32934222, 2020). "However, few studies have been conducted to explore the role of RNF43 in these cancers, so further studies are needed to investigate how certain mutations in RNF43 can possibly lead to the development of these cancers." (PMID 31382613, 2019). "This may occur due to missense mutations of the Wnt pathway regulator, RNF43, which occurs at 24% in these cancers." (PMID 30598662, 2018). "More moderate missense APC mutations occur in BRAF mutant/MSI cancers which may influence the Wnt signal, and it was found that 87% of BRAF mutant/MSI cancers mutate RNF43 which is a negative regulator of the Wnt signal." (PMID 30598662, 2018). "Both, APC and RNF43, are frequently mutated negative regulators of the Wnt/β‐catenin signaling pathway —a pathway that is aberrantly regulated in various cancers." (PMID 29467179, 2018). "The adeno-associated virus system was used to upregulate RNF43 expression in cancer cells." (PMID 28446252, 2017). "This suggests that RNF43 may assist progression of SSA to MSI cancers, whereas RNF43 mutation may be involved at an earlier stage of TSA development." (PMID 27661107, 2016). "Mutation of ZNRF3 in cancer is less frequent as compared with RNF43 mutations." (PMID 27338477, 2016). "RNF43 was frequently mutated in BRAF mutant/MSI cancers (47/54; 87.0%)." (PMID 27661107, 2016). "RNF43 was commonly mutated in BRAF mutant cancers compared to BRAF wild type cancers." (PMID 27661107, 2016). "An RNF43 frameshift mutation (X659fs) occurred in 80% BRAF mutant/MSI cancers." (PMID 27661107, 2016). "BRAF mutant/MSS cancers also commonly showed deletion of the RNF43 locus at 17q22, which may contribute to gene silencing and compensate for the lower RNF43 / ZNRF3 mutation rate in this cancer subgroup." (PMID 27661107, 2016). "MSI cancers were more likely to maintain a normal staining pattern for β-catenin and this was correlated with a lower incidence of abnormal cytoplasmic staining for RNF43, most likely due to the high RNF43 mutation rate in this subgroup." (PMID 27661107, 2016). "We next investigated whether truncated RNF43 interferes with the β‐catenin destruction complex, which provides a central point for Wnt pathway regulation and is commonly targeted by inactivating mutations in cancer." (PMID 32965059, 2020). "Moreover, we show that onco‐RNF43 mutations inhibit differentiation, increase the number of stem cell progenitors, and drive a transcriptional program for proliferation, thus imposing a self‐renewal phenotype onto cancer cells." (PMID 32965059, 2020).
cancer (continued). "Besides, FZD5 antibodies also inhibited the growth of RNF43-mutant CRC-patient-derived organoids suggesting that FZD5 may be associated with RNF43 mutation across multiple cancer types, expanding the use of FZD5 antibody in cancer treatment." (PMID 29789460, 2018). "Furthermore, the novel combination of Porcupine and MEK inhibition resulted in considerable growth reduction, which indicates this may be a promising treatment approach for patients with serrated pathway cancers harbouring RNF43 and/or ZNRF3 mutations." (PMID 27661107, 2016). "KEGG pathway enrichment analysis showed that hsa05206: MicroRNAs in cancer, and hsa04151: PI3K-Akt signaling pathway were significantly enriched in the RNF43-mutated group." (PMID 40860811, 2025). "Truncating mutations that remove at least the C-terminal half of the protein, lead to a defective RNF43 protein, while longer truncated proteins retain partial functionality for which it is still unclear how much Wnt-dependency they confer onto cancers." (PMID 39674817, 2025). "RNF43 regulates Wnt signalling, which is a pathway that has a well-described role in cancer pathogenesis." (PMID 41002577, 2025). "As these novel therapeutics progress into clinical trials, it is important to uncover which RNF43 and ZNRF3 variants observed in cancers, are likely to benefit from such treatments." (PMID 39674817, 2025). "Expression levels of cancer stem cell (CSC) marker genes Lgr5, Smoc2, Axin2, Rnf43, and CD44 were markedly reduced in Prrc2a‐deficient tumors induced by AOM‐DSS treatment." (PMID 39582289, 2025). "The remaining 45 cancers carry additional truncating mutations in either AXIN1, AXIN2 or AMER1, or defective missense or truncating RNF43 mutations." (PMID 39674817, 2025). "Five of the six carriers met the WHO2010 criteria for SPS with a second somatic hit in RNF43 (predominantly LOH) identified in all 22 cancers/polyps analyzed." (PMID 38063999, 2024). "In the context of cancer, ZNRF3 and RNF43 are frequently inactivated by gene deletion, mutation, or other means." (PMID 38260423, 2024). "Strikingly, RNF43 and ZNRF3 mutations are differentially distributed across cancer types, raising questions about their functional redundancy." (PMID 38969364, 2024). "The most common mutation affecting downstream components in the aberrant cancer Wnt/β-catenin signaling pathway is seen in the gene-encoding adenomatous polyposis coli (APC), with such mutations being seen in RNF43-, ZNRF3-, and RSPO3-mediated cancers." (PMID 39125653, 2024). "The modulation of RNF43 gene levels showed that by silencing rnf43 in aggressive cancer cells, sustained surface expression of endogenous PAR2 was observed." (PMID 39125653, 2024). "Loss-of-function mutations in RNF43 and ZNRF3 mediate FZD stabilisation and a WNT-hypersensitive growth state in various cancer types." (PMID 38969364, 2024). "ZNRF3 and RNF43 are closely related transmembrane E3 ubiquitin ligases with significant roles in development and cancer." (PMID 38260423, 2024). "And we raise the question: is RNF43 a monogenetic cause of SPS and can it be applied in broad cancer gene panels?" (PMID 39546056, 2024). "Therefore, a complete understanding of the original RNF43 function and all the events caused by each genetic mutation including not only Wnt but also other signaling pathways will be important for developing the therapy of all cancer types carrying RNF43 mutations." (PMID 38383910, 2024). "To elucidate novel signaling pathways regulated by ZNRF3/RNF43 in cancer, we conducted integrative proteogenomic analyses of human cancer datasets using LinkedOmics." (PMID 38260423, 2024). "We hope that the knowledge obtained from further research in RNF43 will be applied to cancer treatment in the future despite the fully unclear function of RNF43." (PMID 38383910, 2024).